BRCA1 (BRCA1 DNA repair associated)
Diseases named in the same sentence as BRCA1 in open-access papers (continued):
Sharing a sentence is not in itself a finding about the gene and the disease.
breast cancer (continued). "Coffee intake in women with CYP1A2*1F C-allele is associated with both smaller breast size and lower breast cancer risk in BRCA1 carriers." (PMID 24349006, 2013). "Atypical and unusual histologic features of breast cancers in BRCA1 mutation carriers have been reported." (PMID 23374397, 2013). "Because of the very low prevalence of BRCA1/2 germline mutation carriers among unselected breast cancer patients, the study was designed as a case-cohort study in order to acquire a reasonable number of BRCA1/2 tumors." (PMID 23704984, 2013). "Although the breast cancer susceptibility gene BRCA1 is one of the most extensively characterized genetic loci, much less is known about its upstream variable number tandem repeat element, the RNU2 locus." (PMID 24146815, 2013). "The percentage of BRCA1/2 germline mutations in early-onset breast cancer patients ranges widely, from 11 to 24% in different studies." (PMID 23469205, 2013). "Mutations in these genes are rare and early reports suggested that, on average, they are associated with moderate risks of breast cancer (lower than the high breast cancer risks associated with BRCA1 and BRCA2 mutations)." (PMID 23448497, 2013). "Demonstrating proof-of-principle, studies of olaparib, a potent oral PARP inhibitor, have demonstrated monotherapy activity and acceptable toxicity in patients with ovarian or breast cancer who have a germline BRCA1 or BRCA2 mutation." (PMID 24063698, 2013). "Some missense mutations are also pathogenic, eg, 5482G>T in BRCA1 can cause Gly1788Val,17 as has been reported in the Breast Cancer Information Core (BIC)." (PMID 23318652, 2013). "Female carriers of BRCA1 or BRCA2 mutations have a lifetime risk of 49 to 87% for developing breast cancer, wherefore they are offered intensive cancer surveillance as well as risk reducing surgery." (PMID 23704984, 2013). "When I started, the field had just been set alight by the discovery, through genetic linkage analysis of such families, of the genomic location of the first high risk (10- to 20-fold) breast cancer susceptibility gene, BRCA1, on chromosome 17q." (PMID 23339072, 2013). "Zhang Q’s study showed the ectopic expression of BRCA1 was associated with the genesis, progression, and prognosis in young breast cancer patients." (PMID 23915145, 2013). "BRIP1 gene is located on chromosome 17q22, just distal to the BRCA1 gene located at 17q21, a region that shows frequent loss of heterozygosity in breast cancers." (PMID 24040146, 2013). "In our study, expression of KAI1 in samples from BRCA1 mutation carriers seems to be downregulated again with lowest values in patients with a history of previous breast cancer." (PMID 23553196, 2013). "It is well known that the overwhelming majority of people with germline BRCA1 mutations develop basal-like (triple-negative) breast cancer." (PMID 23704974, 2013). "Loss of function of the tumour suppressor BRCA1 (Breast Cancer 1) protein is responsible for numerous familial and sporadic breast cancers." (PMID 23805307, 2013). "According to preliminary data, loss of heterozygosity of the BRCA1 gene is observed in more than half of the cases of sporadic breast cancer and ovarian cancer." (PMID 24325835, 2013). "After modeling a BRCA1/2 cohort from age 25 years, the cumulative risk of developing breast cancer by age 65 years was 42.7% (95% CI: 38.8, 46.7)." (PMID 23837641, 2013). "It is well documented that the breast cancer susceptibility gene BRCA1 is involved in DNA damage repair and cell cycle regulation, but a recent study revealed an interesting link between BRCA1 and the epigenetic regulation of oncomirs." (PMID 24348513, 2013). "Hereditary breast cancer is usually detected in women with family history of breast cancer that was observed among first-degree relatives (mother, sister, and daughter) and is caused by mutations in tumor suppressor genes BRCA1 and BRCA2 in germinal cells." (PMID 24325835, 2013).
breast cancer (continued). "We have identified a novel locus at 1q32, containing the MDM4 oncogene, that is associated with breast cancer risk for BRCA1 mutation carriers (P<5×10−8)." (PMID 23544013, 2013). "Despite characterization of these genetic susceptibility genes, fewer than 10% of all breast cancers are attributable to mutations in BRCA1/BRCA2." (PMID 23922822, 2013). "Mechanism of developing breast cancer is still unclear but the contribution of mutation in BRCA1 and BRCA2 have been reported to be associated with a dominantly increased risk of disease." (PMID 23659667, 2013). "About 10% of breast cancer is attributable to genetic predisposition, with approximately 30% familial cases due to BRCA-1 or BRCA-2 genes mutations." (PMID 23282240, 2013). "Current advanced molecular technologies, including bi-directional sequencing and High Resolution DNA Melting Analysis, allow researchers to retrieve a widespread number of mutations in the BRCA1/2 genes of patients with a familial history of breast cancer." (PMID 24179442, 2013). "The central region of the BRCA1 gene is associated with an increased risk of breast cancer compared to other regions of the gene." (PMID 23941236, 2013). "These variants likely play a role in breast cancer predisposition by deleteriously affecting BRCA1-mediated cell cycle regulation and thus warrant further investigation." (PMID 23704879, 2013). "Mutations of so-called low penetrance breast cancer genes functionally related to BRCA1/2, such as CHEK2, ATM, BRIP1, and PALB2, are rare, but confer an intermediate risk of the disease." (PMID 24205004, 2013). "The group of BRCA1 mutation carriers has been additionally evaluated according to medical history of breast cancer." (PMID 23553196, 2013). "In particular, in BRCA1 mutation carriers, the cumulative life time risk for breast cancer is about 70%; for ovarian cancer 40%; and, in BRCA2 mutation carriers, 50% for breast and 10% for ovarian cancer." (PMID 23644885, 2013). "In some instances, variants have been observed to differentially associate with breast cancer risk in BRCA1 or BRCA2 carriers, and one variant has been reported to specifically associate with BRCA2 mutations." (PMID 24025454, 2013). "Although numerous RNA profiling studies of breast cancers have been published, only a limited number of studies of breast tumors from BRCA1 and BRCA2 mutation carriers exist." (PMID 23704984, 2013). "The prevalence of BRCA1/2 mutation carriers in general population is around 0.2%, and about 5%–10% of all breast cancers and 10%–15% of ovarian cancer cases can be attributed to this risk factor." (PMID 24325835, 2013). "In summary, we have identified a novel locus at 1q32 associated with breast cancer risk for BRCA1 mutation carriers, which was also associated with ER-negative breast cancer for BRCA2 carriers and in the general population." (PMID 23544013, 2013). "BRCA-1-associated breast cancers are sensitive to these agents since double-strand DNA breaks cannot be correctly repaired in cells deficient in homologous recombination repair mechanisms." (PMID 23983689, 2013). "In contrast, among sporadic early-onset breast cancer patients, the frequency of BRCA1/2 mutation ranges from 1–10%." (PMID 23469205, 2013). "Two independent studies have indicated that basal-like Brca1-associated human and mouse mammary tumors originate from luminal epithelial progenitors." (PMID 24171719, 2013). "We identified a novel breast cancer risk modifier locus at 1q32 for BRCA1 carriers (rs2290854, P = 2.7×10−8, HR = 1.14, 95% CI: 1.09–1.20)." (PMID 23544013, 2013).
breast cancer (continued). "We carried out a meta-analysis focusing on the relationship between length of AIB1 gene poly-Q repeat domain as a modifier of breast cancer (BC) susceptibility in patients with BRCA1 and BRCA2 mutation carriers." (PMID 23483928, 2013). "Meta-analysis of RAD51 135G>C polymorphism and breast cancer association according to BRCA1/BRCA2 mutation." (PMID 24040396, 2013). "While exome sequencing of non-BRCA1/2 breast cancer cases is a promising strategy to detect new high-risk genes, rational approaches to the rigorous pre-selection of cases are needed to reduce heterogeneity." (PMID 23383274, 2013). "From the original publication of the two most widely known breast cancer (BC) susceptibility genes, namely BRCA1 and BRCA2, there has been an active pursuit of new genes contributing to the familial BC phenotype." (PMID 23409019, 2013). "There are over 10 genes causing hereditary forms of breast cancer (BC), however only BRCA1- and BRCA2-related disease has been studied with sufficient level of comprehension." (PMID 23548133, 2013). "We therefore attempted to use GINI on lymphoblastoid cell lines (LCLs) from multiple-case, non- BRCA1/2 breast cancer families in order to identify additional high-risk breast cancer susceptibility genes." (PMID 22703186, 2012). "For example, early attempts to develop mouse models of BRCA1-linked breast cancer were unsuccessful." (PMID 22347400, 2012). "The goal of the current study was to evaluate the relationship between breastfeeding and breast cancer risk among women with a BRCA1 or BRCA2 mutation." (PMID 22405187, 2012). "We have previously studied topotecan responses in a genetically engineered mouse model for BRCA1-deficient breast cancer." (PMID 23028879, 2012). "When looking at all of the women in the trial, 41% of the BRCA1- or BRCA2-mutated breast cancer patients had an objective response when assigned 400 mg twice-daily olaparib." (PMID 22295252, 2012). "BRCA1 is a DNA damage repair protein where loss-of-function mutations typically lead to early onset of breast cancer and ovarian cancer." (PMID 22615549, 2012). "For women who had their first breast cancer before the age of 40 years, the cumulative risk of contralateral breast cancer after 25 years was 55.1% for BRCA1, 38.4% for BRCA2, and 28.4% for patients from BRCA1/2 negative families." (PMID 23216834, 2012). "Genotyping was accomplished in 530 sporadic postmenopausal breast cancer cases, 165 familial breast cancer cases (including N = 29, who test positive for BRCA1/2 mutations) and 270 postmenopausal control women using the flurogenic 5' nuclease assay." (PMID 22436609, 2012). "ALDH1 expression is significantly increased in both tumor cells and tumor stroma in breast cancers carrying BRCA1 mutations." (PMID 23077482, 2012). "The prevalence of genetic BRCA1/2 mutation among non-familial patients with high-risk factors in this study was more than three times higher than the 2.6% prevalence observed for BRCA1/2 mutations in sporadic breast cancer patients in Korea." (PMID 22382806, 2012). "Although somatic mutations in BRCA1/2 rarely occur in sporadic breast cancer, a rather high incidence, approaching 20%, of germ-line mutations in BRCA1 or 2 has been reported in patients with TNBC." (PMID 22295242, 2012). "BRCA1 is mutated more frequently in families with both breast and ovarian cancer and more rarely in families with male breast cancer where BRCA2 is predominant." (PMID 22290208, 2012). "It has been proven that bilateral prophylactic mastectomy reduces the risk of breast cancer by 90% in women with intact ovaries and by 95% in women who have undergone both prophylactic mastectomy and oophorectomy in the case of BRCA1/2 gene mutation carriers." (PMID 22503188, 2012). "The breast cancer susceptibility gene 1 (BRCA1) is a known tumor suppressor gene in human breast cancer; however its role in ovarian cancer is not well understood." (PMID 22685544, 2012).
breast cancer (continued). "Here, we utilized a powerful analytical method called Gene Set Enrichment Analysis (GSEA) focusing on several biological pathways: EGF, Stathmin, HER2, BRCA1,Homologous Recombination, which are associated with breast cancer progression." (PMID 22595006, 2012). "Here is why: Lifetime risk for breast cancer of 1 per 8.2 women (12.2% per woman) increases in presence of BRCA1/2 mutations approximately five-fold to ca. 60 percent." (PMID 22984553, 2012). "The KOHBRA study was designed by the Korean Breast Cancer Society to investigate the prevalence of BRCA1/2 mutations in several groups of subjects seen in high-risk breast cancer clinics in Korea between 2007 and 2010." (PMID 22382806, 2012). "Results of a phase II trial detailed how olaparib is effective in breast cancer patients with a BRCA1 or BRCA2 mutation and advanced disease." (PMID 22295252, 2012). "In this study, a woman diagnosed with BRCA1 associated breast cancer between the age of 25 to 29 was calculated to have a 5-year and 10-year risk for contralateral breast cancer of 16% and 29%, respectively." (PMID 23216834, 2012). "Woman carrying mutations in either BRCA1 or BRCA2 have an 80 to 90% lifetime risk of developing breast cancer and a 20 to 50% chance of developing ovarian cancer." (PMID 23171648, 2012). "Germline mutations in the currently known high risk-breast cancer genes (such as BRCA1/2) are common in familial breast cancer, but they can explain, at best, 20–25% of the overall excess familial risk." (PMID 22701724, 2012). "According to the literature, 10% of ovarian cancer cases and 3–5% of breast cancer cases are associated with BRCA1 or BRCA2 mutations." (PMID 22737296, 2012). "A recent single-institution study showed that 50% of high-risk patients with TNBC had mutations in BRCA1/2, but notably, 76% of this cohort had a family history of breast cancer." (PMID 23116406, 2012). "In the presence of a BRCA1 mutation, women have a 70-80% lifetime risk of developing breast cancer and a 50% risk of developing ovarian cancer." (PMID 22737296, 2012). "Several reports on BRCA gene mutation in Korean breast cancer patients have been published over a decade since a first report of BRCA1 among Korean pedigrees in 1995." (PMID 22382806, 2012). "Most cases of hereditary breast cancer are attributable to germline mutations in one of two major breast cancer-predisposing genes, BRCA1 or BRCA2 (BRCA1/2)." (PMID 22257650, 2012). "Previous reports of BRCA1/2 mutations in Korean breast cancer patients were limited by small sample sizes, and the studies were performed individually at various sites with different screening methods." (PMID 22382806, 2012). "Our study shows that among women with early-onset breast cancer (≤35 years old) and with a family history of breast cancer, a higher prevalence of BRCA1 mutations is present in women with TNBC compared with women with non-TNBC." (PMID 23116406, 2012). "This approach had been adopted for hereditary breast cancer due to concerns about the psychological consequences of BRCA1/2 genetic susceptibility testing." (PMID 22569005, 2012). "Previous candidate-gene DNA sequencing studies have implicated homologous recombination in breast cancer susceptibility, and BRCA1 and BRCA2 themselves are players in this pathway." (PMID 23028381, 2012).
breast cancer (continued). "Radiation therapy (RT) after breast conservation therapy has recently been linked with significant reduction in risk of ipsilateral breast cancer among BRCA1 mutation carriers." (PMID 23210696, 2012). "We recently performed chemosensitivity assays in the BRCA-deficient human breast cancer cell line HCC1937 in order to further assess the specific antiproliferative potential of MET relevant to BRCA1 deficiency." (PMID 26097796, 2012). "For example, some studies showing genetic variants of BRCA1 (rs799917) or Cyclooxygenase-2 (COX-2) (rs2745559) have been shown to associate with breast cancer susceptibility." (PMID 22778704, 2012). "Lastly, our study provides the first estimate of the potential breast cancer modifying effect of 6q22.33 in carriers of BRCA1 mutations." (PMID 22768030, 2012). "PHD3 and FIH are responsible for the HIF-1α degradation and modulation observed in BRCA1-mutated breast cancers." (PMID 22007214, 2012). "On the other hand, the prevalence of BRCA1/2 mutations among breast cancer patients with family history of breast or ovarian cancers was 24.8% in the KOHBRA study interim report." (PMID 22382806, 2012). "Relationship between duration of breastfeeding and risk of breast cancer among BRCA1 and BRCA2 mutation carriers." (PMID 22405187, 2012). "T allele at 936 position in 3′UTR was reported to be associated with reduced risk of breast cancer in Austrians, Turkish, Chinese and also Polish with BRCA1 mutation." (PMID 23203097, 2012). "These genes would be possible candidates for founder mutations of BRCA1/2 in high-risk Korean breast cancer patients." (PMID 22382806, 2012). "BRCA1 mutation accounts for nearly half of familial breast cancers (OMIM 604370), but BRCA1 is also down-regulated in sporadic breast tumors without germline mutation." (PMID 23173005, 2012). "For instance, the prevalence of BRCA1/2 mutations in male breast cancer patients as well as in patients with breast and ovarian cancer in this study must be interpreted with caution due to the very small number of subjects." (PMID 22382806, 2012). "Women with BRCA1 mutations have an exceptional high risk of breast cancer and few options to reduce this risk." (PMID 26097796, 2012). "BRCA1 (breast cancer 1, early onset) missense mutations have been detected in familial breast and ovarian cancers, but the role of these variants in cancer predisposition is often difficult to ascertain." (PMID 22646717, 2012). "In summary our intriguing and novel results point to the potential broader utility of PARP inhibitors in breast cancer beyond hereditary BRCA1-and BRCA2-deficient tumors by combining it with EGFR inhibitors such as lapatinib." (PMID 23071597, 2012). "BRCA1/2 mutations of bilateral breast cancer in other ethnic countries showed both 29.6% in high-risk Jewish families and in Polish patients with having 46.9–82.4% positive familial history." (PMID 22382806, 2012). "For example, loss of heterozygosity (LOH) at BRCA1 is common in both inherited and sporadic breast cancer." (PMID 22347400, 2012). "Specifically, failure of terminal differentiation after pregnancy in BRCA1 mutation carriers resulted in an increased risk of breast cancer." (PMID 22405187, 2012). "For unaffected relatives carrying a BRCA1/2 mutation, cumulative breast cancer risk at the age of 70 years ranges from 40-80%." (PMID 22569005, 2012). "Women with detectable BRCA1 methylation in the peripheral blood have an increased risk of early onset breast cancer." (PMID 22570110, 2012). "In order to determine the spectra and frequency of BRCA1/2 mutations within the Lebanese population, we studied a cohort of 72 Lebanese unrelated patients with breast cancer." (PMID 22713736, 2012). "DSB preferentially causes breast cancer cells to undergo apoptosis, especially when relevant repair pathways, such as those mediated by BRCA1, are perturbed." (PMID 23203101, 2012).